YY1 (YY1 transcription factor)
Diseases named in the same sentence as YY1 in open-access papers (continued):
Sharing a sentence is not in itself a finding about the gene and the disease.
cancer (continued). "We next explored the correlation between YY1/PEBP1 mRNA levels and immune infiltration in pan-cancer." (PMID 37894300, 2023). "Our study further detected several correlations between YY1 and PEBP1 mRNA expression and immune infiltration across different cancers." (PMID 37894300, 2023). "Therefore, it is crucial to meticulously delineate YY1 protein structure and the dynamic alteration of its protein–protein interactions (PPIs) in each cancer type, which may help to not only better understand its role in diverse cancer types but also design individual therapeutic strategies." (PMID 36880159, 2023). "YY1 is an important mediator of enhancer–promoter interactions, and the expression of YY1 and MAFF in the cancer-epithelial cells was confirmed using the matching scRNA-seq dataset." (PMID 37685859, 2023). "Taken together, we used multiple prognostic datasets for pan-cancer and preliminarily revealed that the high mRNA levels of YY1 and PEBP1 significantly correlate with a poor prognosis for different cancer patients." (PMID 37894300, 2023). "Within the cancer-enriched constituent enhancers of SE60, we found SOX4, ATF4, and YY1 as the top three predicted transcription factors." (PMID 35869079, 2022). "This approach aims to target miRNAs to downregulate YY1 expression and result in the inhibition of EMT in cancer cells." (PMID 35719931, 2022). "From all of the listed reports, it is easy to abstract that the manifestations of these four factors (YY1, Kcnq1ot1, miR-506-3p and SYPL1) in the malignant phenotypes of cancers are consonant with the findings in the present work." (PMID 35778739, 2022). "In general, YY1, Kcnq1ot1, miR-506-3p and SYPL1 have the applicable prospects in treating cancers, but the mechanism focused on their loop feedback in OSCC was rarely elaborated." (PMID 35778739, 2022). "Yin-Yang 1 (YY1), which can act as a transcriptional activator of oncogenes or a repressor of cancer suppressors, is a critical promoter of hepatocarcinogenesis." (PMID 34998399, 2022). "IIPA found that SFPQ interacts with many important proteins, such as YY1, RTN4, RICTOR, HDACs, BMI1, and HNRNPC, which are important in the development of cancer." (PMID 35707369, 2022). "Cisplatin, the first-line drug for the chemotherapy of many cancers, including NSCC, was found to upregulate YY1 expression." (PMID 35408813, 2022). "Extensive evidence confirms that YY1 expression is significantly increased in HCC tissue and is closely correlated with the expression of other cancer-related genes." (PMID 34998399, 2022). "Yin Yang 1 (YY1), a GLI-Krüppel zinc finger protein, is a DNA/RNA-binding transcription factor important in tumorigenesis and cancer progression." (PMID 34834139, 2021). "The analysis of YY1 and BCL2L15 expression following CRC samples stratification based on cancer aggressiveness (i.e., metastasis vs. primary, mesenchymal vs. epithelial) was demonstrated to be a significant discriminator." (PMID 34445183, 2021). "YY1 is a zinc finger transcription factor that belongs to the GLI-Krüppel gene family 8 and dysregulated in assorted human cancers." (PMID 34863279, 2021). "Both Yin Yang 1 (YY1) and enhancer of zeste homolog 2 (EZH2) are oncogenes with overexpressed statuses in cancers." (PMID 34065631, 2021). "Among these genes, PICALM (targeted by EP300), DDX6 (targeted by YY1) and LYL1 (targeted by LMO2) are reported on the COSMIC cancer gene list." (PMID 32850701, 2020). "Overexpression of transcription factors YY1, HSF1 and SP1, known to regulate Ub gene expression, is a predictor of poor prognosis and shorter survival in several cancers." (PMID 32751694, 2020). "OBP peptide disrupts YY1 interaction with other oncogenic proteins including AKT and thereby prevents cancer growth." (PMID 31824839, 2019).
cancer (continued). "Cancer stemness is also maintained by other factors, such as Golgi phosphoprotein 3 (GOLPH3), yin and yang 1 (YY1), and neurofilament light (NEFL)." (PMID 31861937, 2019). "We also analyzed RNA-seq data available in TCGA (The Cancer Genome Atlas) to determine any possible correlations in RNA expression of CARM1 and YY1 in different cancer types." (PMID 31217904, 2019). "Existing evidences report that several key transcription factors contribute to the up-regulation of lncRNA in human cancers, such as SP1, ELK1, STAT3 and YY1." (PMID 31713587, 2019). "We have accumulating evidence demonstrating that YY1, as a downstream target of NF-κB, can be modulated by RKIP-mediated NF-κB inhibition, thus abolishing its activity on cancer cell resistance." (PMID 30149591, 2018). "Another miRNA-related autophagy control mechanism involves Yin Yang 1 (YY1), a transcription factor and an epigenetic regulator that is upregulated in various cancer types." (PMID 28459042, 2017). "Meanwhile, the roles of YY1 and miR-584-3p in regulating the MMP-14 expression warrant further investigation in other types of cancers." (PMID 28827574, 2017). "A close association was revealed between the frequency of expressions of YY1 and SOX2 as well as SOX2 and OCT4 in all cancers analyzed." (PMID 27225481, 2016). "The Cancer Atlas feature was interrogated to assess the antibody staining of YY1, SOX2, OCT4, NANOG and BMI1 in different cancer types." (PMID 27225481, 2016). "Data mining from the proteomic tissue-based datasets from the Human Protein Atlas were used for protein expression patterns of YY1 and the four CSC markers in 17 types of cancer, including both solid and hematological malignancies." (PMID 27225481, 2016). "Conversely, overexpression of YY1 in the cancer cells suppresses FEN1 expression and sensitizes cancer cells to DNA damaging drugs." (PMID 25885449, 2015). "After overcoming the barrier of the 14q32 region, it seems that changes in the expression of YY1 transcription factor and YY1-related genes are jointly responsible for driving cancer cells into their new cell state." (PMID 25115389, 2014). "RYBP is a key interaction partner of YY1, and it is also a component of the Polycomb repressive complex 1 (PRC1), a well-known chromatin-modifying complex that monoubiquitinates histone H2A, thus repressing gene expression during development and in cancer." (PMID 40867231, 2025). "Several key biological pathways are enriched for cancer-specific sets of isoTWAS-prioritized genes, including cell cycle and mitosis regulation, DNA and RNA binding, immune pathways, as well as downstream targets of cancer-relevant transcription factors like ESR1, RUNX2, and YY1." (PMID 40775447, 2025). "In addition to direct repression of RKIP by YY1, YY1 and RKIP engage in an indirect regulatory loop that reinforces cancer progression." (PMID 41327312, 2025). "Additionally, YY1 has an inhibitory effect on the RAS/MAPK pathway and epithelial-to-mesenchymal transition (EMT) depending on the cancer context." (PMID 41327312, 2025). "This indicates that the combination of YY1 and MYC might be the most synergistic in promoting cancer reversion." (PMID 39840939, 2025). "This suggests that YY1 and TFAP2 competition might influence a broader transcriptional regulation network in HPV-induced cancer." (PMID 40953061, 2025). "This review systematically examines the contrasting roles of YY1 and RKIP in cancer pathogenesis (e.g. cell proliferation and cell cycle, angiogenesis, immune cells infiltration and immunosuppressive TME, check point inhibitors, resistance to apoptosis, cell energetics, etc.)." (PMID 41327312, 2025).
cancer (continued). "To confirm that IL‐32 is the downstream effector of YY1‐mediated PC effects on EGFR‐mutated cancer cell sensitivity to TKI, we exposed these cells to CM from YY1‐depleted PCs in the presence of TKI drugs, with or without IL32 treatment." (PMID 39435643, 2024). "The manipulation of YY1 expression in different cancer cell lines has been shown to have both negative and positive outcomes on the prevalence of cancer." (PMID 39796650, 2024). "While further research is necessary to confirm the relationship between YY1, TGF-β, and PD-L1, there is promising evidence that this connection could influence cancer immunotherapy." (PMID 38539569, 2024). "Furthermore, YY1 plays a dual role in regulating IFN-γ both positively and negatively in different cancers." (PMID 38539569, 2024). "Lastly, both YY1 and YAP/TAZ pathways have also been extensively studied in cancer cells." (PMID 39496834, 2024). "Furthermore, they found a correlation between YY1 expression and LAG-3 expression within these ESCA cancer cells as well." (PMID 39796650, 2024). "Based on these results, we propose that targeting the YY1/GHITM/Notch1 axis could decrease the malignant behaviour of KIRC cells and potentiate antitumour efficacy of cancer therapy, which provides a promising and novel therapeutic strategy for KIRC patients." (PMID 38588015, 2024). "Yin Yang-1 (YY1) is a multifunctional transcription factor that plays a considerable regulatory role in multiple biological processes, consequently influencing the pathological processes of cancers by binding to numerous proteins and DNA." (PMID 36952101, 2023). "Additionally, YY1/PEBP1 expression and methylation displayed connections with genomic alterations across different cancer types." (PMID 37894300, 2023). "Yin-Yang 1 (YY1), a ubiquitously expressed and multifunctional zinc-finger transcription factor, plays a crucial role in many biological processes, including cancer cell progression." (PMID 37724907, 2023). "We first assessed the percentage of YY1 and PEBP1 (heterozygous and homozygous) CNVs in pan-cancer." (PMID 37894300, 2023). "The expression of CP2c and YY1 mRNA showed a negative correlation when analyzed not only in cancer tissues with high YY1 expression (p = −0.611) but also in all cancer tissues regardless of YY1 expression (p = −0.701)." (PMID 37444605, 2023). "Although inhibitors targeting YY1 is not currently developed, the applications of ncRNAs in cancer treatment are reported, some of which have entered a clinical trial stage." (PMID 36880159, 2023). "In particular, the protein expression of CP2 and YY1 also showed a significant negative correlation in all cancer tissues (p = −0.952)." (PMID 37444605, 2023). "YY1 also promotes PVT1 expression via binding to its promoter to further affect autophagy through the mTOR pathway, leading to increased invasion and adhesion activity in cancer." (PMID 37724907, 2023). "Subsequently, we used HPA database to analyze the RNA and protein expressions of YY1 in various cancer cell lines, pathological tissues, and normal human tissues." (PMID 35791393, 2022). "Further investigations are warranted to clarify how the JAC1-YY1 interaction triggers YY1 ubiquitination and degradation, and whether the anti-proliferation and pro-apoptotic effects of JAC1 on TNBC are suitable for other types of cancer." (PMID 35383155, 2022). "Abnormalities in YY1, Kcnq1ot1, miR-506-3p, and SYPL1 have been manifested in cancer progression." (PMID 35778739, 2022). "Although the E3 ubiquitin ligase Smurf2 is reported to target and degrade YY1 protein in several cancers, unfortunately, we did not obtain positive evidence of Smurf2 on YY1 in TNBC." (PMID 35383155, 2022). "However, an experimental approach is needed to verify the cooperation between H2A.Z and TFs such as SP2, ZNF384, YY1, NRF1, and NFYA in the transcriptional misregulation in cancer." (PMID 35317119, 2021).
cancer (continued). "From this we speculated that YY1 could positively regulate MRPL42, thereby enhancing the cancer-promoting effect of MRPL42." (PMID 33758616, 2021). "Together, our data positions YY1 as an important TP73-AS1 regulator, demonstrating that TP73-AS1 is expressed in the natural and pathological aging brain, including during neurodegeneration and cancer." (PMID 34115613, 2021). "Meanwhile, our findings also suggested that cancer cells might share similar regulatory mechanisms with PTEN, YY1, and CDK6 controlled by miR-34a." (PMID 33796457, 2021). "Given that cytoplasmic lncRNAs function as competing endogenous RNAs in cancer, we speculated that LINC02532 would regulate YY1 expression in this manner." (PMID 34834139, 2021). "Even in the absence of ongoing clinical trials with YY1 direct inhibitors, several YY1-inhibiting agents are under investigation for their potential use as anti-cancer therapies, either alone or in combination with other drugs." (PMID 32226547, 2020). "Yin Yang 1 (YY1), a dual function transcription factor, is known to regulate the transcriptional activation and repression of many genes that are involved in various homeostatic processes and diseases including cancer." (PMID 32635336, 2020). "However, the function of HOXD3 in cancer onset and upstream/downstream regulation maintenance requires further investigation; especially, the relationship between HOXD3 and YY1 in HCCs has rarely been studied." (PMID 32557953, 2020). "Of note, next to YY1, YY2 can also be upregulated in cancer cells." (PMID 33102493, 2020). "Although YY1 has been demonstrated to regulate survivin expression in other models, the mechanism is not totally clarified, as it seems to rely on the specific cancer nature." (PMID 32899428, 2020). "YY1 was shown to bind to Feline sarcoma-related (FER) promoter and repress its expression; where FER has been shown to induce the phosphorylation of STAT3, which in turn enhances the expression of MMP2 and cancer progression." (PMID 31824839, 2019). "YY1 is a zinc finger protein and a member of the GLI-Kruppel family that can activate or inactivate gene expression depending on its interacting partners, YY1 is overexpressed in multiple cancer types and correlates with poor clinical outcomes." (PMID 31921637, 2019). "As results, we found that cancer tissues displayed a significantly higher YY1 level in patients with metastasis than those without metastasis (P < 0.01)." (PMID 28485541, 2017). "Although the expression and regulatory roles of CP2c and YY1 have been reported individually for several types of cancer, co-regulation of these proteins in carcinogenesis has not been specifically explored as of yet." (PMID 28412749, 2017). "The first genome-scale analysis of transcription factor binding sites in cancer found that binding by transcription factors such as Sp1, NRF1, and YY1 could protect CpG island gene promoters from cancer-specific hypermethylation." (PMID 25994056, 2015). "Vice versa, YY1, a known repressor related to cancer, has almost no gains in non-dbSNP variations, while dbSNP variations have an almost equal amount of gains and losses." (PMID 26562774, 2015). "Down-regulation of PSCA expression by YY1 may similarly reduce PSCA expression and promote disease progression in these cancers." (PMID 22536409, 2012). "Notably, insights from cancer biology, where both immune and metabolic networks are commonly dysregulated, have identified two key regulators: Raf kinase inhibitor protein (RKIP) and its counter-regulator Yin Yang 1 (YY1)." (PMID 41459495, 2025). "Hence, as anti-cancer immunotherapy has gained momentum with the development of new immunotherapeutic strategies approved by the FDA for various cancers, targeting YY1 in combination with these new approved immunotherapies should result in an effective treatment of the GBM." (PMID 38893192, 2024).
cancer (continued). "Hence, these data indicate that YY1 may serve as a negative regulator of MGP and that it may play oncogenic roles in different cancers." (PMID 39684309, 2024). "The researchers analyzed the effect of the YY1 on biological processes using the DAVID method, and these results suggested that the promotion of glutamine metabolism by YY1 may promote the progression of ESCC by affecting cancer pathways." (PMID 37081988, 2023). "YY1 is overexpressed in NSCLC and co-expressed in the NSCLC gene network, probably related with the activation of cell proliferation and invasion, forming a regulatory loop with cancer stem cell transcription factors (SOX2, OCT4, and BMI1) in the NF-kB/PI3K /AKT axis." (PMID 36661515, 2023). "However, cancer-promoting transcription factors cannot be easily targeted due to their nuclear localization, YY1 is predominantly present in nuclei and not easily targeted." (PMID 36059990, 2022). "The expression of E6 and E7 oncoproteins in cancer cells might be regulated through several different mechanisms, and the role of YY1 in this process has not been clearly defined yet." (PMID 35408813, 2022). "Additionally, both EZH2 and YY1 have been reportedly overexpressed in most cancer types; therefore, the YPB and OPB peptides can very likely exhibit inhibitory activities against other cancers." (PMID 34065631, 2021). "Finally, YY1 may positively regulate the expression of another transcription factor KLF4, showing a dual role in cancer, with a possible prognostic value." (PMID 32899428, 2020). "Thus, YY1 can regulate expression of both protein-coding genes and noncoding genes such as miRNAs in human cancer cells." (PMID 30737371, 2019). "YY1 expression is elevated in PIN and intermediate stage disease, and its interaction with AR may result in increased PSCA expression in PIN and well-differentiated cancers." (PMID 22536409, 2012). "In order to further explore the molecular function of YY1 in ESCA, we analyzed the effects of YY1 gene on biological process by the DAVID approach, and the results suggest that glutamine metabolism may promote ESCC progression by influencing pathways in cancer." (PMID 35359580, 2022). "While YY1 was shown to constitutively form the repressive YY1-RelA complex in MM, the signaling pathway/s involved in this remained elusive and whether YY1-RelA complex plays a pro-tumorigenic role in other cancer models has not been explored." (PMID 31824839, 2019). "The double knockdown of YY1 and MYC resulted in a significant decrease in the cancer score to 0.056, corresponding to the disappearance of the cancer attractor and the emergence of dominant normal and near‐normal attractors in the landscape." (PMID 39840939, 2025). "The detailed mechanisms whereby YY1 recruits co-repressors (e.g. HDACs, EZH2) to the RKIP promoter is better understood in some cancer systems but not in others." (PMID 41327312, 2025). "The experiments also demonstrated a co-occurrence of the activated TERT and DNA repair processes, and a co-activation of ALT and various oncogenic pathways, including E2F/DP1, MYC, YY1, ERK, NFκB, HIF1α and WNT, revealing that TERT inhibition alone is not enough to suppress cancer cells’ growth." (PMID 36615513, 2022). "Alternatively, YY1 could recruit enzymes able in turn to modify the chromatin (es., EZH2, HDAC) and, hence, orchestrate changes in the epigenetic status of the BCL2L15 gene, as it was observed in other cancer and non-cancer models." (PMID 34445183, 2021).